CD163 (CD163 molecule)
Diseases named in the same sentence as CD163 in open-access papers (continued):
Sharing a sentence is not in itself a finding about the gene and the disease.
tumor (continued). "In contrast, CD14+ monocytes and CD163+ and CD68+ macrophages predominated in the immune landscape of the FGF23-secreting tumour microenvironment, accounting for 30.74%, 23.23%, and 16.96% of all detectable immunopositive tumour cells, respectively." (PMID 40981193, 2025). "Our results showed that CD68+ and CD163+ TAMs were more abundant in the tumor mucosa than in the normal mucosa, with higher levels in late-stage CRC." (PMID 41573553, 2025). "Tumor conditioning upregulates macrophage CD163, CD206, CD80, and LILRB1 without impairing phagocytosis; CD47 blockade similarly enhances A2780 cell clearance in conditioned and control macrophages." (PMID 41280929, 2025). "Similarly, in mIDH1 iCCA, the strongest interactions were between tumor cells and αSMA+ fibroblasts, as well as tumor cells and CD68+/CD163- macrophages." (PMID 39969434, 2025). "We observed with label-free SHG imaging that the primary OS tumour edge was surrounded by a thick Col-I band, which potentially did not allow invasion of CD163+ to penetrate the OS tumour." (PMID 41315643, 2025). "OSCC Tumor Resection specimens after IT showed a significantly higher CD163/CD11c expression ratio compared to OSCC Resections without IT (mean 0.73 vs. 0.30; p=0.036)." (PMID 40297579, 2025). "Studies have demonstrated that TAMs, particularly those expressing CD163, can physically impede CD8+ T cells from reaching tumor cells and penetrating the tumor parenchyma, thereby limiting their movement and effectiveness within the tumor stroma." (PMID 40423041, 2025). "Recognizing the interplay between sCD163, which acts as a surrogate of CD-163 positive TAMs burden, with CCL2 and CCL4 that enforce TAMs’ tumor infiltration, could reveal new biomarkers." (PMID 39996747, 2025). "CD163 immunoreactivity in tumor tissue in the absence of IBA1 upregulation was a rare finding and potentially related to incipient necrosis based on morphological criteria." (PMID 40191733, 2025). "Ki67 (a proliferation marker) and CD163 co-staining showed no co-localisation, indicating that the observed proliferation was due to tumour cells, not M2-polarised macrophages." (PMID 40420192, 2025). "CD163+ TAMs secrete pleiotrophin (PTN), which binds to its receptor on GSCs, protein tyrosine phosphatase receptor type Z1 (PTPRZ1), promoting self-renewal and sustainability that support tumor progression." (PMID 40361384, 2025). "In OSCC, TAMs express receptors such as CD206, CD163, and Toll-like receptors, as well as cytokine and chemokine receptors including IL-1R, CSF-1R, and CCR family members, which serve as biomarkers for TAM quantification and tumor dissemination." (PMID 40948759, 2025). "We analyzed the relationship between tumor‐infiltrating immune cells (CD4, CD8, FOXP3, CD163‐positive cells) and proteins (TGFβ1 and its downstream signal, SMAD3) expression and survival after the start of combined therapy with immune checkpoint inhibitors plus chemotherapy in SCLC." (PMID 41187938, 2025). "We also found extensive and frequently diffuse extracellular CD163 deposition, especially in hypocellular necrobiotic tumor regions where IBA1 was typically absent." (PMID 40191733, 2025). "However, macrophages from external sources, such as blood and perivascular spaces, which typically produce CD163, contribute to the TAM cell pool, especially in necrobiotic tumor tissue." (PMID 40361384, 2025). "Similarly, in NSCLC tumour tissues, GMIP shows a strong spatial correlation with the M2 macrophage markers CD163 and CD68." (PMID 40275529, 2025). "TAMs can polarize into multiple subtypes, influenced by factors such as colony‐stimulating factor 1 (CSF‐1) and chemokine (C‐C motif) ligand 2 (CCL2), and often express M2‐like markers including CD206, CD163, Arginase 1 (ARG1), and IL‐10, all of which promote tumor progression." (PMID 40553053, 2025). "For verification, we evaluated the expression levels of CD163- and CD8-positive cells in the tumor." (PMID 39652104, 2025).
tumor (continued). "Some studies indicate that high densities of CD163+ cells in the tumor stroma but not in the tumor nest is associated with poor OS, PFS and/or BCSS, while other studies indicate that high CD163+ density in the tumor nest associate with unfavorable OS." (PMID 39751847, 2025). "Across these specimens, TREM2 predominantly localized to areas with CD163+ macrophages rather than cytokeratin (PanCK)-positive tumor cells." (PMID 39744236, 2025). "Combined, these results indicate that CD163+ immune cells in the tumor nest of PT associate with worse outcome (PFS and OS) in MBC, while the prognostic relevance of CD163 at other tumor sites and in the PT stroma was not significant." (PMID 39751847, 2025). "The abundance of CD163-negative PNF-associated macrophages, derived from circulating monocytes, correlated with tumor size." (PMID 40992926, 2025). "For ER-positive MBC, high density levels of CD163+ immune cells in the tumor nest and stroma did not significantly correlate to PFS or OS." (PMID 39751847, 2025). "These 3D networks exhibit the gradient distribution of cellular structure (e.g. CD68+CD163+ macrophages, and B/T cells) and molecular markers (e.g. PD-L1, LAG-3, TIM-3), indicating that TLSs may play a dynamic coordinating role in anti-tumor immune response." (PMID 41041059, 2025). "In this retrospective study, we analyzed clinical data, tumor extension, cystic characteristics and immunohistochemical markers for inflammation (CD68, CD163, CD3, CD8) and proliferation (MIB-1) as potential factors influencing the EOR in 1007 surgically treated primary sporadic VS." (PMID 41044688, 2025). "Similarly, analysis of data from patients with CRC in TCGA and GEO databases showed that CD14, CD163, and CD206 expressions were higher in peritumor intestine than in tumor." (PMID 40756343, 2025). "A positive correlation (r = 0.5716) was observed between CD163− tumor macrophages as a percentage of live cells in tumors and tumor volume; CD163+ macrophages were anticorrelated with tumor volume, but only as a percentage of CD45+ cells, suggesting modulation of resident macrophage production." (PMID 40992926, 2025). "Most of the 313 new disease links belonged to the DisGeNET class neoplasms (n = 40; EGFR, ERBB2, KITLG, AREG) but also to immune diseases (n = 29; FAS), neurological diseases (n = 13; PNPLA6), and cardiovascular diseases (n = 13; CD163)." (PMID 40593564, 2025). "In CRC patients, CD163+ TAM expression was significantly higher in stages III–IV compared with I–II (P < 0.05), in those with lymph node metastases (P < 0.05), and in patients with low tumor differentiation (P < 0.05)." (PMID 41395618, 2025). "Positive staining of PD-L1, CD31 (partial +), CD34, CD68, CD163, vimentin and SMA detected in the tumor tissue, indicating that vascular endothelial cells, TAMs and fibroblasts may participate in the pathogenesis of ENKTL." (PMID 40433378, 2025). "We also found extensive and frequently diffuse extracellular CD163 deposition, especially in hypocellular necrobiotic tumor areas where IBA1 was typically absent." (PMID 40191733, 2025). "Since UPS and MFS cancer cells are known to express myeloid markers like CD68 and CD163, we reviewed the imaging data to ensure that the observed myeloid cell counts were not confounded by tumor cells expressing these markers." (PMID 40601026, 2025). "Tumor infiltrating immune cell analysis by immunohistochemistry showed no changes in the number of CD163+ M2-like macrophages, CD4+ or B220+ cells in the different therapy groups." (PMID 38824552, 2024). "Analysis in CRC also shows a significantly higher frequency of CD4 + Foxp3 + Treg cells and CD68 + CD163 + M2 macrophages in intratumoral TLS compared to peritumoral TLS, suggesting a potential correlation between peri-tumor TLS and the immunosuppressive environment within the tumor." (PMID 39068459, 2024).
tumor (continued). "Our data demonstrates that baseline expression of CD163, a myeloid cell marker that can be used to estimate myeloid burden in tissue, is expressed at a similar level in tumor tissue at the time of resection in survivors and non-survivors." (PMID 39346903, 2024). "Immunofluorescence confirmed that IL-33 induced an accumulation of M2 macrophages, whereas CD163 was absent in tumor tissues of 615-line mice treated with anti-CSF1R." (PMID 38238529, 2024). "We analyzed the experimental results of IHC and observed that the positive staining (brown area) of Ki-67, CKAP2, CD163, and CD31 was reduced after CKAP2 knockdown in the tumor tissues of mice, showing the inhibitory effects of CKAP2 knockdown on proliferation and angiogenesis of tumor cells." (PMID 39403723, 2024). "Some researchers suggest that the proportion of CD206+ cells, as opposed to CD163+ cells, increases in correlation with tumor advancement." (PMID 39703508, 2024). "Differences were also observed in the extravascular matrix pattern, tumour-infiltrating lymphocytes, and tumour-infiltrating CD68+/CD163+ macrophage subsets; although, these differences were not consistent between Regions A and B across the tumours." (PMID 39766052, 2024). "As biliary dysplasia progresses to an invasive state, CD68 + and CD163 + macrophage infiltration increases in the tumor mesenchyme rather than the epithelium, indicating temporal heterogeneity in immune cell distribution within the TMEs from different origins." (PMID 39068459, 2024). "While the expression of CD163+ in the tumor tissues did not demonstrate any significant differences, it was significantly downregulated in the spleen tissues of the treatment group." (PMID 39337506, 2024). "The AFX test result was negative for both AE1/AE3 and CAM5.2 and positive for both CD68 and CD163, indicating that it was a nonepithelial tumor with histiocytic traits." (PMID 39171331, 2024). "Notably, the levels of CD68 + CD163-, indicative of M1 macrophages, were higher in the primary MEN1/DAXXmut (PM) group compared to its metastatic (MM) counterpart (p = 0.280 in tumor, p = 0.332 in stroma)." (PMID 38448900, 2024). "With regard to tumor-promoting or immunosuppressive cells, CX3CR1 is reportedly expressed by Tregs, MDSCs, and TAMs; therefore, we analyzed CD3 expression in Tregs, CD14 and CD163 expression in M-MDSCs and TAMs, and LOX-1 expression in PMN-MDSCs." (PMID 38433196, 2024). "Together, our exploratory findings support the notion that CD163+ TAMs play a critical role in orchestrating lymphogenesis in VSCC by exhibiting enhanced VEGF-A expression and triggering increased VEGF-A levels in VSCC tumor cells." (PMID 38407373, 2024). "Similar to our results, the previous study also reported a higher number of CD163+ macrophages in the stroma compared with the tumor but did not further evaluate this as a predictive factor." (PMID 38407373, 2024). "The levels of soluble CD163 reflect the burden of TAMs in the tumor microenvironment, whose roles have not been fully elucidated yet." (PMID 38474108, 2024). "In the work described, we observed that indirect co-culture of CBX2 expression in cancer cells led to the increase of CD163- and CD206-expressing TAM, highlighting the contribution of secreted factors from the cancer cells regulating the macrophage phenotype toward tumor promotion." (PMID 38984891, 2024). "By way of illustration, P09 showed B cell and CD163+macrophages dominated neighborhoods, not restricted to the invasive margin but also located in the tumor center." (PMID 39053947, 2024). "In addition, the expression levels of CD163, CD68, CD44, and CD133 in GBC tissues were significantly correlated with tumor metastasis." (PMID 39138521, 2024). "CD163 expression was increased, and the classic activation marker HLA-DR was decreased in monocytes induced by the CM of EBV-positive tumour cells compared with EBV-negative tumour cells." (PMID 39267775, 2024).
tumor (continued). "Within the tumor center, CD68 counts were correlated with CD4, CD8, and CD163 of the same region." (PMID 39338178, 2024). "Our findings indicated a significantly (p < 0.05) higher expression of protein biomarkers associated with the presence and activity of immune cells, including CD45, CD3, CD68, CD163, CD11c, CD8, HLA-DR, CD40, PD-L1, and IDO1, in the tumor compartments of patients with CR compared to those with PD." (PMID 39049036, 2024). "Selection of regions of interest (ROIs) in participant FFPE tissue was guided by immunofluorescent staining of CD163 for myeloid cells (some macrophages, MDSC, microglia), CD3 (T lymphocytes), and GFAP (tumor and astrocytes) in conjunction with an expert neuropathologist." (PMID 39346903, 2024). "When we compared macrophages and FABP4 expression in tumor tissues in patients with or without tumor metastasis, we showed that tumors from metastatic patients had higher expression of CD163+ macrophages and FABP4 expression." (PMID 39513934, 2024). "Twelve patients with a CD68/CD163 ratio > 1 in the tumor center showed significantly longer OS than those without dominant M1-polarized macrophages." (PMID 39630300, 2024). "CD163+ macrophages affect PD-L1 expression in tumor cells, and CD163+ M2 macrophages exert immunosuppressive effects by activating JAK/STAT signaling to produce IL-10 and promote PD-L1 expression in tumor cells." (PMID 38893259, 2024). "We hypothesised that not only the recruitment of monocytes but also the local proliferation of CD163+ TAMs and/or their monocytic precursors within the TME might contribute to the accumulation of these TAMs in human tumours." (PMID 38903497, 2024). "We did not observe any prognostic role of baseline CD8, CD68 or CD163 expression in the tumor microenvironment." (PMID 38339307, 2024). "Patients with positive SOX12, Foxp3, CD11b, and CD163 expression or negative CD8 expression showed tumor‐aggressive tendency and poor prognosis." (PMID 39072947, 2024). "Therefore, sections containing tumor and tumor-adjacent adipose tissue were stained with antibodies against CD68 and CD163 to detect M2-like polarized macrophages." (PMID 39456610, 2024). "While the low frequency of Tregs was associated with improved PFS in the tumor microenvironment, no predictive value of CD8, CD68, CD163, PD-1 and PD-L1 expression was observed in our study." (PMID 38339307, 2024). "Furthermore, based on mIF analysis, the PCR group showed higher cell densities of CD8+, PD-L1+, and CD8+PD-L1+ in the tumor region, while showing lower cell densities of CD3+Foxp3+, Foxp3+, and CD163+." (PMID 38887237, 2024). "We did observe some expression of CD16 in CD163+ TAMs, so we cannot rule out the possibility that some of the CD163+ TAMs that co-express CD16 derive from the CD16+ (non-classical & intermediate) monocytes recruited into the tumour." (PMID 38903497, 2024). "Furthermore, tumor‐infiltrated T cells (CD3+ and CD8+) and CD11c+ macrophages were significantly increased in the response group, while CD163+ macrophages and FOXP3+ Treg cells were decreased after NACT." (PMID 38778559, 2024). "The tumor-infiltrating lymphocytes (TILs) in the central and peripheral regions of the tumors were analyzed separately using markers including CD20, CD3, CD68, CD8, CD4, CD163 and FOXP3." (PMID 39198311, 2024). "In our cohort of 10 patients, we did not see any correlation between CD163 or CD90 expression and tumour stage, gender or SDH mutational status, however this will need further examination in a larger cohort of patients." (PMID 39619326, 2024). "Multiplex immunofluorescence staining of the surgically resected tumor showed a locally dense accumulation of layers of wound stroma dominated by CD163+/CD206+ M2-like Mφ adjacent to the biopsy cavity, while M2-like Mφ were much more sparsely distributed in the peripheral tumor stroma." (PMID 38969944, 2024).
tumor (continued). "Tumour macrophage numbers were not related to HIV status, but low pro-inflammatory (M1) macrophage numbers (CD68 + CD163 −) were significantly associated with poorer outcomes (HR 2.02, p = 0.03)." (PMID 39259401, 2024). "It is, thus, interesting to note that in our study, CD163 apparently stains heme complexes within tumor-adjacent acinar cells, rather than depicting individual immune cells (arrows)." (PMID 39723364, 2024). "We aimed to perform an immunohistochemical characterization of a panel of immune biomarkers (CD3, CD4, CD8, CD163, programmed death ligand 1 and programmed death 1) of 30 GBM patients to determine the tumor immune infiltrate and the distribution of the principal immunological markers." (PMID 39594814, 2024). "The relationships between CD16+ and CD163+ macrophages and K17 expression were independent of other clinicopathologic features, including tumor grade, pathological stage, treatment history, histologic variant, and mutational status (data not shown)." (PMID 38730319, 2024). "Tumor segments in Type 2 OC (HGSC) were shown to have stronger infiltration of immune cells, including CD3, CD4, CD11c, CD163, CD56 and CD80, suggesting that both pro- and anti-inflammatory immune phenotypes are elevated inside the tumor nests compared to Type 1 OC." (PMID 39026018, 2024). "Our subsequent correlation analysis revealed that increased numbers of CD163+ TAMs were associated with higher LVD, regardless of their tissue compartment (tumor and stroma: q = 0.06; Benjamini–Hochberg corrected Mann–Whitney U test)." (PMID 38407373, 2024). "In mice, compared with NSCLC mice, the tumor volume and weight of the IFN-γ group were increased, the expression of CD163, CD206, IDO1, Ki-67 and Bcl-2 in tumor tissue was upregulated, the expression of Bax and C-caspase 3 was downregulated, and apoptosis was reduced." (PMID 38254043, 2024). "In all the samples we collected, high expression of CD47 was connected to CD163+ macrophage infiltration.In summary, the expression of CD47 may regulate TME through immune cell infiltration, thus regulating tumor progression." (PMID 37719086, 2023). "Furthermore, CD206+ and CD163+ cells, which are markers of M2 macrophages, were significantly suppressed in the M-DM1 group in tumor tissues." (PMID 37122692, 2023). "Therefore, we investigated the expression of CD163+ TAMs, CD68+ M1s, CD8+ lymphocytes, and PD-L1 and CD25+ Treg cells within the primary tumours." (PMID 36857852, 2023). "We investigated the bone remodeling markers RANK/RANKL/OPG, the endothelial glycoprotein CD146, and biomarkers of the immune environment (CD163 and CD68 of macrophages, CD4+ and CD8+ of tumor-infiltrating lymphocytes (TILs), and an immune checkpoint PD-1/PD-L1)." (PMID 36831348, 2023). "Additionally, we examined other immune-related cells in the tumor microenvironment, including CD4+ T-cells (Th1, Th17, and Treg) and CD163+ cells." (PMID 37790758, 2023). "Moreover, despite the co-occurrence of CD163+ macrophages and CD8+ T cells in low-grade tumours, their tendency to directly interact was strongest in high-grade tumours and decreased as tumors became lower grade." (PMID 36725934, 2023). "The strong positive staining of CD163 (++) and CD206 (+) could be seen in the tumor tissue of RBE+M2 co-implantation group." (PMID 37809069, 2023). "Somewhat surprisingly, our data showed that high levels of stromal CD163+ TAMs in NAC-treated tumor residues correlated with the absence of metastasis within three years of primary surgery." (PMID 38090569, 2023). "While they assessed the spatial distribution resulting in higher CD163+ cell density in the invasion front, it was not the focus of their investigation so ratios between tumor center and invasion were not tested for significance." (PMID 36836239, 2023).